SSBP1 (single stranded DNA binding protein 1)
Description:
Binds preferentially and cooperatively to pyrimidine rich single-stranded DNA (ss-DNA). In vitro, required to maintain the copy number of mitochondrial DNA (mtDNA) and plays a crucial role during mtDNA replication by stimulating the activity of the replisome components POLG and TWNK at the replication fork. Promotes the activity of the gamma complex polymerase POLG, largely by organizing the template DNA and eliminating secondary structures to favor ss-DNA conformations that facilitate POLG activity. In addition it is able to promote the 5'-3' unwinding activity of the mtDNA helicase TWNK. May also function in mtDNA repair.
Synonyms: Mt-SSB; MtSSB; SSBP; OPA13; SOSS-B1
Tractability: PROTAC: ubiquitination databases record sites on it; its protein half-life has been measured.
Gene: Protein-coding gene on chromosome 7 (141,737,456 to 141,787,922, forward strand). Ensembl gene ENSG00000106028.
Subcellular location: Mitochondrion; Mitochondrion matrix, mitochondrion nucleoid
Subcellular location (Human Protein Atlas): Mitochondria; Calyx; Principal piece
Pathways (Reactome):
DNA Replication: Strand-asynchronous mitochondrial DNA replication
Metabolism of proteins: Mitochondrial protein degradation
Organelle biogenesis and maintenance: Transcriptional activation of mitochondrial biogenesis
Gene Ontology:
Molecular function: chromatin binding; identical protein binding; protein binding; protein homodimerization activity; RNA binding; single-stranded DNA binding; enzyme activator activity
Biological process: mitochondrial DNA replication; positive regulation of helicase activity; positive regulation of mitochondrial DNA replication; protein homotetramerization; DNA replication
Cellular component: extracellular exosome; mitochondrial nucleoid; mitochondrion; nucleus; mitochondrial matrix
Genetic constraint (gnomAD): Loss-of-function variants: 8 observed, 16.67 expected, observed/expected ratio (o/e) 0.48, 90% interval 0.28 to 0.87. The upper end of that interval is the gene's LOEUF score, 0.87, which puts it in group 3 of 6, group 1 being the genes least tolerant of losing a copy. Missense variants: 78 observed, 123.26 expected, observed/expected ratio (o/e) 0.63, 90% interval 0.53 to 0.76. Synonymous variants: 42 observed, 40.96 expected, observed/expected ratio (o/e) 1.03, 90% interval 0.8 to 1.33.
Gene-disease validity (ClinGen):
ClinGen rates the evidence that SSBP1 causes each of these diseases.
optic atrophy 13 with retinal and foveal abnormalities (autosomal dominant): Strong.
Leigh syndrome (autosomal dominant): Limited. A progressive neurological disease defined by specific neuropathological features associating brainstem and basal ganglia lesions.
Homologues: Orthologues: chimpanzee SSBP1 (100% identical), mouse Ssbp1 (92% identical), dog SSBP1 (90% identical), macaque SSBP1 (87% identical), dog SSBP1 (82% identical), pig SSBP1 (82% identical), rat Ssbp1 (82% identical), tropical clawed frog ssbp1 (78% identical), guinea pig SSBP1 (73% identical), zebrafish ssbp1 (72% identical), Drosophila melanogaster mtSSB (39% identical), Caenorhabditis elegans mtss-1 (27% identical).
Diseases named in the same sentence as SSBP1 in open-access papers:
SSBP1 is named in the same sentence as 53 diseases in open-access papers, as found by Europe PMC text mining. Sharing a sentence is not in itself a finding about the gene and the disease. The quoted sentences say what the papers report.
optic atrophy (19 papers, 2019 to 2025). A disorder characterized by loss of optic nerve fibers. "The autosomal dominant mutations, R38Q and R107Q, in SSBP1, were first identified in five unrelated families, all of whom exhibited optic atrophy." (PMID 41226312, 2025). "In this case, the variants (Sentence 6) have a ‘Positive_Correlation’ relationship with ‘optic atrophy’, as stated in the title (Sentence 0 ‘SSBP1 mutations’)." (PMID 40662797, 2025). "Nevertheless, several of the phenotypes-associated SSBP1 mutations seem to be tissue specific, primarily including optic atrophy and sensorineural deafness." (PMID 39104869, 2024). "Until now, fewer than 15 mutations in SSBP1 have been identified, and the majority of these patients present with optic atrophy, sensorineural deafness, mitochondrial myopathy, and kidney failure." (PMID 39104869, 2024). "Optic atrophy is the predominant phenotype observed in patients with SSBP1 mutations, accompanied by a range of neurological symptoms." (PMID 39104869, 2024). "Mutations in SSBP1 are associated with a variety of tissue-specific phenotypes, but primarily present as optic atrophy." (PMID 39104869, 2024). "WES detected a pathogenic heterozygous SSBP1 missense variant (NM_003143.3) C.320G >A (p.Arg107Gln), confirming the diagnosis of optic atrophy 13 with retinal and foveal abnormalities (MIM #165510)." (PMID 36993412, 2023). "SSBP1 variants are associated with a form of inherited optic neuropathies that have phenotypic variabilites manifesting as isolated optic atrophy, optic atrophy combined foveopathy or photoreceptor degeneration." (PMID 36993412, 2023). "The variants in SOX5 (n = 1), SPG7 (n = 1), and SSBP1 (n = 1) genes were responsible for cases of other dominantly inherited optic atrophies." (PMID 36071901, 2022). "In summary, we report seven additional patients harboring SSBP1 variants with optic atrophy and retinal dystrophy." (PMID 34905022, 2021). "Previous work has identified a set of pathogenic mutations in the SSBP1 gene that cause severe phenotypes in affected individuals, including optic atrophy and kidney insufficiency." (PMID 34215584, 2021). "As previously reported and observed in the current study, optic atrophy and retinal dystrophy are the major clinical features recognized in patients harboring SSBP1 variants with RGC, photoreceptors and RPE being the site of highest SSBP1 expression." (PMID 34905022, 2021). "Dominant pathological variants in SSBP1 have recently been shown to induce optic atrophy, hearing loss, and foveopathy with mtDNA depletion, and recessive variants express features of Pearson, Kearns-Sayre, and Leigh syndrome." (PMID 33426505, 2020). "In our study, optic atrophy is clearly unexpected for mutations in SSBP1, an mtDNA maintenance–related gene." (PMID 31550237, 2020). "The predominant clinical symptom exhibited by the present cohort of patients with SSBP1 mutations is an optic atrophy." (PMID 31550237, 2020). "In this work, we identified SSBP1 as a gene associated with tissue-specific mtDNA depletion diseases and with an unexpected dominant phenotype: an autosomal dominant nonsyndromic optic atrophy with foveopathy." (PMID 31550237, 2020). "Recently, two studies have reported pathogenic variants in SSBP1 associated with hearing loss, optic atrophy, and retinal degeneration." (PMID 31479473, 2019). "Patients with SSBP1 mutations typically suffer from optic atrophy and have also been reported to experience neurological dysfunction mainly affecting the visual system (retinopathy, foveopathy, ptosis, ophthalmoplegia) and auditory system (sensorineural hearing loss)." (PMID 41226312, 2025). "In this study, we identified a novel heterozygous mutation in SSBP1 (c.272G>A:p.Arg91Gln) in one family exhibiting symptoms of sensorineural deafness, optic atrophy, macular dystrophy, early cataract, and mitochondrial myopathy, which are all compatible with mitochondria disease." (PMID 39104869, 2024).
optic atrophy (continued). "Among 60 published patients with missense SSBP1 variants, optic atrophy was present in 95% of them." (PMID 36993412, 2023). "Additionally, some phenotypes can be inherited in both dominant and recessive fashions, such as optic atrophy caused by variants in SSBP1 (single-stranded DNA-binding protein 1)." (PMID 36553587, 2022). "Almost all families show dominant inheritance of non-syndromic autosomal OA and rod-cone dystrophy in addition to the optic atrophy is common, indicating that retinal neurons other than RGCs are susceptible to mitochondrial dysfunction induced by SSBP1/OPA13 mutations." (PMID 34867178, 2021). "A dominant variant in SSBP1 has been reported to induce optic atrophy and foveopathy." (PMID 33426505, 2020). "Moreover, our results add SSBP1 to the increasing list of dominant optic atrophy–causing genes." (PMID 31550237, 2020). "Fundus changes in patients with variants in seven genes exhibited optic atrophy plus retinal degeneration in our in-house cohort, including ACO2, FDXR, NBAS, OPA3, RTN4IP1, SSBP1 and C12ORF65." (PMID 39423307, 2025). "This has been clearly contradicted by the SSBP1 gene example, where mtDNA depletion leads to defective bioenergetics, leading simultaneously to optic atrophy and retinal dystrophy, as well as the case of RTN4IP1 mutations and other rare conditions." (PMID 35008635, 2021). "Congruently, as for the SSBP1-mutant patients, from the clinical standpoint in addition to optic atrophy, some retinal symptoms may also occur, such as peculiar retinal dystrophic changes." (PMID 34056600, 2021). "Screening of SSBP1 in a cohort of 174 European probands with inherited optic atrophy and without genetic diagnosis identified 4 additional German families, families B, C, D, and E, with an SSBP1 mutation." (PMID 31550237, 2020). "MtSSB (SSBP1, encoded by SSBP1) is an indispensable component of the mtDNA replication machinery and defects in SSBP1 may lead to an isolated or syndromic phenotype characterized by optic atrophy and retinal dystrophy." (PMID 34905022, 2021). "The SSBP1 gene should, therefore, be considered for NGS panels used to screen for isolated or syndromic optic atrophy and retinal dystrophy." (PMID 34905022, 2021). "SSBP1 is essential for mitochondrial DNA replication and maintenance, with defects leading to a spectrum of disease that includes optic atrophy and/or retinal dystrophy, occurring with or without extraocular features." (PMID 34905022, 2021).
breast carcinoma (6 papers, 2017 to 2023). "Mitochondrial Src is high in breast cancer cells of triple negative subtype, and targets to phosphorylate mitochondrial single stranded DNA-binding protein (SSBP1), a regulator of mtDNA replication." (PMID 35625853, 2022). "Mitochondrial Src is high in breast cancer cells of triple negative subtype, and this Src phosphorylates mitochondrial single stranded DNA-binding protein (SSBP1), a regulator of mtDNA replication." (PMID 35625853, 2022). "A recent report has suggested that SSBP1 acts as a tumor suppressor to restrain mammary epithelial cell phenotype transdifferentiation and breast cancer metastasis, and thereby its decreased expression contribute to the worse survival of breast cancer patients." (PMID 29340022, 2017). "SSBP1, TXNRD1, SLC25A5, DDOST, SEH1L, and MCM2 had a significant effect in at least 50% of breast cancer cell lines in the CRISPR-Cas9 and/or RNAi screening data." (PMID 37445737, 2023).
cervical cancer (6 papers, 2017 to 2024). A primary or metastatic malignant neoplasm involving the cervix. "Most of the circRNAs reported in cervical cancer progression are cell cycle supporters such as circZFR, which upregulates many cell cycle regulators via binding to single-stranded DNA-binding protein 1 (SSBP1)." (PMID 38892280, 2024). "Subsequent research revealed that knock-down of endogenous SSBP1 dramatically enhanced the sensitivity of cervical cancer cells to chemotherapy." (PMID 29340022, 2017). "Besides, circZFR bound with SSBP1, thereby inducing the assembly of CDK2/cyclin E1 complexes, which induced p-Rb phosphorylation, thus releasing activated E2F1 leading to cell cycle progression and cell proliferation in cervical cancer." (PMID 36008845, 2022).
retinal degeneration (6 papers, 2019 to 2025). Degeneration of the retina. "For instance, in PMID: 31298765, the abstract states: ‘Sentence 0: SSBP1 mutations in dominant optic atrophy with variable retinal degeneration...." (PMID 40662797, 2025). "The reason for the earlier retinal degeneration changes for those with SSBP1 variants in our cohort is not clear, but environmental factors as well as genetic background might contribute to the difference." (PMID 39423307, 2025).
Leigh syndrome (5 papers, 2019 to 2021). "However, a mutation in the nuclear gene SSBP1 (Single-Stranded DNA-Binding Protein 1) was recently described, causing SLSMD with clinical symptomatology of Pearson Syndrome, KSS and Leigh syndrome." (PMID 33105723, 2020).
Retinal dystrophy (5 papers, 2021 to 2025). Retinal dystrophy is an abnormality of the retina associated with a hereditary process. "Our study demonstrates the highly variable retinal dystrophy phenotype, provides new evidence of intrafamilial variability and additional evidence of autosomal recessive inheritance in SSBP1-disease." (PMID 34905022, 2021). "Recently, missense variants in SSBP1 have been reported to cause autosomal dominant mitochondrial optic atrophy and retinal dystrophy with or without mitochondrial depletion." (PMID 34905022, 2021). "The value of comprehensive electrophysiological phenotyping in syndromic diseases is highlighted in cases of SSBP1-related disease and ROSAH (Retinal dystrophy, Optic nerve oedema, Splenomegaly, Anhidrosis and Headache)." (PMID 38862643, 2024). "The predominant genes for retinal dystrophy are FDXR, SSBP1, ACO2 and RTN4IP1." (PMID 39423307, 2025).
colorectal cancer (4 papers, 2017 to 2022). A primary or metastatic malignant neoplasm that affects the colon or rectum. "The upregulation of SSBP1 is associated with the aggressiveness of osteosarcoma cells; whereas, its depletion triggers cell death in colorectal cancer cells by affecting the mitochondrial proteome." (PMID 36180956, 2022). "Previous studies have shown that the expression level of SSBP1 is upregulated in colorectal cancer." (PMID 35180892, 2022). "Therefore, upregulation of SSBP1 in tumor tissue predicts poor prognosis in patients with colorectal cancer." (PMID 35180892, 2022). "In colorectal cancer, IL-6-STAT3-FOXP1 axis-mediated transcriptional activation of SSBP1 is beneficial for cancer cell proliferation and tumor growth." (PMID 35180892, 2022).
hearing loss (4 papers, 2018 to 2024). "Here we describe a heterozygous start loss mutation in SSBP1 co-segregating with hearing loss in a maternal pedigree transmitting the m.1555A>G variant." (PMID 29182774, 2018). "However, the underlying mechanism of how hearing loss is linked to SSBP1 mutations remains poorly understood." (PMID 39104869, 2024). "A review of the clinical history of hearing loss in the family suggested that the proband's hearing loss may have a different etiology to that of his father, and he was the first in the family affected with an ocular phenotype in keeping with SSBP1-disease." (PMID 34905022, 2021).
osteosarcoma (4 papers, 2017 to 2025). A usually aggressive malignant bone-forming mesenchymal neoplasm, predominantly affecting adolescents and young adults. "Apart from that, a study showed that SSBP1 expression was also elevated in human osteosarcoma cells and the expression level correlated with an aggressive phenotype." (PMID 29340022, 2017). "To this end, we evaluated the viability of the human osteosarcoma 143B cells after inactivating TFAM, POLRMT, TFB2M, POLG, POLG2, or SSBP1 with CRISPR-Cas9." (PMID 35883613, 2022).
dominant optic atrophy (3 papers, 2020 to 2025). "Our study showing that mutations in SSBP1 cause a form of dominant optic atrophy frequently accompanied with foveopathy brings insights into mtDNA maintenance disorders." (PMID 31550237, 2020). "Identification of mutations in SSBP1 in families with dominant optic atrophy." (PMID 31550237, 2020). "Here, we report heterozygous mutations in the mitochondrial single-stranded DNA-binding protein single-strand binding protein 1 (SSBP1) in 5 unrelated families with nonsyndromic dominant optic atrophy that in half of the cases is associated with a striking occurrence of foveopathy." (PMID 31550237, 2020). "SSBP1- and OPA1-related dominant optic atrophies share common characteristics, including the early onset before the age of 10 years, bilateral and symmetrical mild to severe visual loss, and large intra- and inter-familial variability, including asymptomatic carriers." (PMID 34548540, 2021).
deafness (2 papers, 2020 to 2024). An inherited or acquired condition characterized by the complete loss of the ability to hear from one or both ears. "The identification of a pedigree in which deafness manifested when the m.1555A>G variant was co-inherited with a loss-of-function SSBP1 variant suggests that SSBP1 may be a phenotypic modifier of m.1555A>G-associated deafness." (PMID 33426504, 2020). "Sensorineural deafness was frequently reported, consistent with the localization of SSBP1 expression in the inner ear." (PMID 39104869, 2024).
lung carcinoma (2 papers, 2017 to 2019). "Similarly, a markedly decline in SSBP1 expression was observed in lung cancer and down-regulation of SSBP1 significantly increased radio-sensitivity in cancer cells." (PMID 29340022, 2017). "The subsequent mechanism research demonstrated that SSBP1 may act as a tumor suppressor to control tumorigenesis and progression, and decreased expression of SSBP1 significantly increased the sensitivity to ionizing radiation in lung cancer." (PMID 29340022, 2017).
melanoma (2 papers, 2018). A malignant, usually aggressive tumor composed of atypical, neoplastic melanocytes. "On the contrary, analysis of SSBP1 properties and its negative correlation with migration ability uncover an onco-suppressor gene in melanoma." (PMID 29545914, 2018).
schizophrenia (2 papers, 2016 to 2020). A major psychotic disorder characterized by abnormalities in the perception or expression of reality. "The mitochondrial-related proteins (ATP5H, SSBP1, SLC25A4 and NDUFV2) previously shown to be differentially expressed in the PSD in schizophrenia were also differentially expressed in the PSD in bipolar disorder." (PMID 27898073, 2016).
triple-negative breast carcinoma (2 papers, 2022). An invasive breast carcinoma which is negative for expression of estrogen receptor (ER), progesterone receptor (PR), and human epidermal growth factor receptor 2 (HER2). "SSBP1 is a suppressor of triple-negative breast cancer metastasis." (PMID 36180956, 2022). "However, in highly metastatic triple-negative breast cancer, SSBP1 expression is downregulated, and a low expression level of SSBP1 is associated with poor patient prognosis." (PMID 35180892, 2022).
atherosclerosis (1 paper, 2017). A disease characterized by the build-up of fatty material and calcium deposition in the arterial wall resulting in partial or complete occlusion of the arterial lumen.
E. coli infection (1 paper, 2022). "Here, the expression of nuclear genes POLG, SSBP1, TWNK, and TOP1 during E. coli infection was consistent with that of mtDNA." (PMID 36430657, 2022).
gastric cancer (1 paper, 2017). A primary or metastatic malignant neoplasm involving the stomach. "However, effects of single nucleotide polymorphisms (SNPs) in SSBP1 gene on gastric cancer (GC) prognosis are still unknown." (PMID 29340022, 2017). "And more notably, the lower expression of SSBP1 in gastric cancerous tissues indicated the biological plausibility, for the G allele of rs6976500 was associated with the worse prognosis of GC, and drove significantly lower leuciferase expression." (PMID 29340022, 2017).